CCL7 (C-C motif chemokine ligand 7)
Description:
Chemotactic factor that plays an important role in immune regulation. Attracts monocytes, eosinophils, basophils, and T-cells to sites of inflammation or infection. Upon binding to various chemokine receptors including CCR1, CCR2, CCR3, and CCR5, facilitates immune cell migration by guiding them to infected tissues. Interacts with CCR2 to facilitate the release of monocytes from the bone marrow into the bloodstream, maintaining monocyte homeostasis. In turn, monocytes recruited to inflamed or injured tissues can differentiate into macrophages or dendritic cells, which are essential for immune defense and tissue repair. Through CCR1, contributes to macrophage polarization via NF-kappa-B activation which leads to the release of inflammatory factors. In the trigeminal ganglion neurons, activates ERK via CCR2 and CCR3 to enhance neuronal excitability, which contributes to the maintenance of trigeminal neuropathic pain. Additionally, modulates the early immune response in the skin, preventing pathogen dissemination while maintaining cutaneous immune control.
Synonyms: MCP-3; MCP3; SCYA6; SCYA7; NC28; FIC; MARC
Tractability: Small molecule: a high-quality ligand is known. Antibody: its Gene Ontology location is reachable by antibodies, with high confidence; UniProt places it where antibodies can reach, with medium confidence; UniProt predicts a signal peptide or a membrane-spanning region.
Target class: Secreted protein
Gene: Protein-coding gene on chromosome 17 (34,270,221 to 34,272,242, forward strand). Ensembl gene ENSG00000108688.
Subcellular location: Secreted
Pathways (Reactome):
Signal Transduction: Chemokine receptors bind chemokines
Gene Ontology:
Molecular function: CCR1 chemokine receptor binding; chemokine activity; protein binding; CCR chemokine receptor binding; CCR2 chemokine receptor binding
Biological process: cytoskeleton organization; eosinophil chemotaxis; positive regulation of cell migration; positive regulation of inflammatory response; positive regulation of natural killer cell chemotaxis; regulation of cell shape; antimicrobial humoral immune response mediated by antimicrobial peptide; cell-cell signaling; chemokine-mediated signaling pathway; chemotaxis; inflammatory response; intracellular calcium ion homeostasis; monocyte chemotaxis; signal transduction; cellular response to ethanol; immune response; response to gamma radiation
Cellular component: extracellular region
Genetic constraint (gnomAD): Loss-of-function variants: 6 observed, 6.37 expected, observed/expected ratio (o/e) 0.94, 90% interval 0.51 to 1.73. That is too few expected variants to judge how well the gene tolerates losing a copy. Missense variants: 126 observed, 107.98 expected, observed/expected ratio (o/e) 1.17, 90% interval 1.01 to 1.35. Synonymous variants: 42 observed, 39.42 expected, observed/expected ratio (o/e) 1.07, 90% interval 0.83 to 1.38.
Homologues: Orthologues: chimpanzee CCL7 (99% identical), macaque CCL7 (91% identical), guinea pig CCL7 (64% identical), mouse Ccl7 (62% identical), rabbit CCL7 (60% identical), rat Ccl7 (60% identical), zebrafish cxcl32b.1 (35% identical). Paralogues in human: CCL2 (74% identical), CCL11 (69% identical), CCL8 (65% identical), CCL13 (63% identical), CCL23 (40% identical), CCL16 (36% identical), CCL4 (36% identical), CX3CL1 (36% identical), CCL15 (35% identical), CCL21 (35% identical), CCL24 (34% identical), CCL3L3 (34% identical), and 14 more.
Diseases named in the same sentence as CCL7 in open-access papers:
CCL7 is named in the same sentence as 290 diseases in open-access papers, as found by Europe PMC text mining. Sharing a sentence is not in itself a finding about the gene and the disease. The quoted sentences say what the papers report.
COVID-19 (115 papers, 2020 to 2025). A disease caused by infection with severe acute respiratory syndrome coronavirus 2. "Further studies are needed to examine the specific roles of CD8 TEM cells, CCL7, and other candidate features, to identify new diagnostic and therapeutic avenues for patients with long-term cardiac sequelae of COVID-19." (PMID 39073768, 2024). "Severe cases of COVID-19 also display higher levels of CCL7, CCL3 and CXCL9 compared to mild and moderate cases." (PMID 33613280, 2020). "Regarding the “HALLMARK_INFLAMMATORY_RESPONSE” gene set, MAFB and MAF were found to oppositely regulate the expression of a cluster of chemokine-encoding genes (CXCL10, CCL2, CCL7, CXCL9) that are associated to the COVID-19 “cytokine storm”." (PMID 33312178, 2020). "Additionally, studies have demonstrated that in COVID-19 patients, the increase in viral load corresponds to the upregulation of critical chemokines, including CCL7, CCL2, CXCL8, and others." (PMID 38812521, 2024). "Severe COVID-19 patients were reported to over-express CCL7 in lung macrophages." (PMID 38543303, 2024). "In BAL fluid, only the levels of CCL8, CXCL10, and CCL7 were significantly lower, and the levels of IL-10 were higher, in patients with COVID-19 after they received corticosteroids compared with those who did not receive corticosteroids (q < 0.05, Mann-Whitney)." (PMID 38502186, 2024). "Three chemokines, CXCL13, CXCL10, and CCL7 were selected for predicting critical COVID-19." (PMID 37069249, 2023). "Additionally, elevated levels of CCL-7 were measured in bronchoalveolar lavage fluid (BALF) samples of COVID-19 patients compared to BALF samples of influenza patients." (PMID 37917760, 2023). "Importantly, among the 14 overlapping proteins, those three chemokines, CXCL13, CXCL10, and CCL7 were selected for predicting both severe and critical COVID-19." (PMID 37069249, 2023). "Furthermore, genes encoding CCL7, CCL8, and CCL13 were also found in bronchoalveolar lavage (BAL) in patients with COVID-19." (PMID 36851766, 2023). "The role of neutrophils in the pathogenesis of fatal COVID-19 could also be suggested as CCL7 contributes to the accumulation of these granulocytes in the lung." (PMID 35386707, 2022). "Together, excessive M-CSF-driven monocyte/macrophage proliferation and CCL2/CCL7 activation and chemotaxis could be the mechanism of severe and fatal COVID-19 pathogenesis." (PMID 35386707, 2022). "Analysis of 48 cytokines in the plasma of 50 COVID-19 patients showed that CXCL10 is an important biomarker for disease severity, and its increase was associated with an elevation in CCL7 (monocyte-chemotactic protein 3 (MCP3))." (PMID 35062368, 2022). "Previous studies reported that COVID-19 is frequently associated with a massive production of 14 cytokines including IFN-γ, IL-1RA (IL1RN), IL-2RA, IL-6, IL-10, IL-18, HGF, MCP-3 (CCL7), MIG (CXCL9), M-CSF (CSF1), G-CSF (CSF3), MIG-1a (CCL3), CTACK (CCL27), and IP-10 (CXCL10)." (PMID 34262555, 2021). "While CXCL9, CXCL10 and CXCL11 expression levels were increased both in moderate and severe disease compared to healthy levels, IL1β, IL6, TNF as well as CCL2, CCL3, CCL4 and CCL7 were expressed at higher levels in lung macrophages from patients with severe COVID-19." (PMID 34367190, 2021). "We have found fifteen cytokines that remain upregulated in convalescent COVID-19 individuals one month after infection (IL-1α, IL-3, IL-10, IL-12p70, CCL7, IFN-α2, bFGF, LIF, TRAIL, IL-2, IL-4, IL-5, IL-12p40, IL-17 and MIF) indicating a strong activation of the immune response." (PMID 34681885, 2021). "Serum CCL3 and CCL7 levels were higher in male than female COVID-19 patients." (PMID 33613280, 2020). "Furthermore, in a kinetic study, the plasma CXCL8, CCL2 and CCL7 levels were higher in fatal cases compared to the mild and/or severe cases of COVID-19." (PMID 33613280, 2020).
COVID-19 (continued). "Overall, the combination of elevated blood CCL7 levels and decreased CD8 TEM cell counts were the most highly predictive markers of abnormal cardiac MRI findings, providing new insight into a potential underlying aetiology of unexplained cardiac symptoms post-COVID-19." (PMID 39073768, 2024). "Likewise, higher levels of CCL2, CCL7, CCL20, and CXCL10 were associated with lower blood lymphocyte count and higher inflammatory markers (CRP and ferritin), which are clinical markers of severe disease and poorer outcome in COVID-19." (PMID 33704068, 2021). "Genes in the subnetwork of the CCL family showed different expression levels in the four groups of COVID-19 severity; in particular, OSM, CCL3, CCL7, and IL2RA showed higher expression in the high-severity COVID-19 samples." (PMID 40362649, 2025). "Reassuringly, our main conclusions regarding CCL7 and CD8 TEM cells as predictors of cardiac MRI abnormalities remained consistent for both the whole cohort and those with long COVID-19." (PMID 39073768, 2024). "In fact, when compared to controls, amniotic fluid from COVID-19-affected pregnancies demonstrated elevated levels of several pro-inflammatory cytokines, including IL-12 p40, CCL4, CCL7, CCL13, TNF, IL-1a, IL-17A, and IL-17E." (PMID 39390219, 2024). "We note the differential expression of many inflammatory CC chemokines (CCLs) in severe COVID-19, including CCL2, CCL3, CCL8, CCL3L1 and CCL7, and CXC chemokines such as CXCL2 and CXCL8." (PMID 39187683, 2024). "It has been revealed that elevated blood CCL7 levels and decreased CD8+ TEM cell counts were the most clinically characterized markers predicting COVID-19-related cardiac MRI abnormalities." (PMID 39444690, 2024). "Monocyte/macrophages in COVID-19 bronchoalveolar fluid from patients with severe COVID-19 were shown to express CCL2 and CCL7." (PMID 37892134, 2023). "Cytokine IFNA7, as well as chemokines CXCL13, CXCL10, CCL7, and CCL8 were present in the proteins selected for predicting severe COVID-19." (PMID 37069249, 2023). "Post–COVID-19 MDMs showed higher expression of proinflammatory chemokines (CCL2, CCL8, and CCL7), driving neutrophil recruitment, including in COVID-19." (PMID 36668902, 2023). "In addition, severe COVID-19 patients BAL alveolar macrophages (n = 88) are characterized by a cluster activation, involving genes encoding several pro-inflammatory mediators such as CCL7, CCL8 and CCL13, that can mediate recruitment and activation of monocytes and T cells." (PMID 36941580, 2023). "Among the modified genes, CCL2, CCL7, and CCL8 were increased in post-COVID-19 monocytes, similar to levels in monocytes from patients with severe acute forms of COVID-19." (PMID 38203577, 2023). "Alongside, we observed a high expression of cytokines (CCL3, CCL4, CCL5, CCL7, CCL18 and CCL20) in the CD4+ TCM, Classical monocytes and NK cells in the COVID-19 patients." (PMID 36532041, 2022). "A set of cytokines were upregulated in SputnikV immunized individuals (IL-1α, IL-3, IL-10, IL-12p70, CCL7, IFN-α2, bFGF, LIF and TRAIL), where nine of them were similar to that in convalescent COVID-19." (PMID 34681885, 2021). "In severe COVID-19 lung macrophages displayed high expression of IL-1β, IL-6, TNF-α and various chemokines (CCL2, CCL3, CCL4, CCL7, CXCL9, CXCL10 and CXCL11)." (PMID 34054832, 2021). "Moreover, cytokines MCP3/CCL7, MIG/CXCL9, IL1 beta, and SCF, key in viral infection immune responses, exhibited reduced levels in COVID-19 patients with sputum production during the acute phase in our study." (PMID 39052548, 2024). "A positive correlation of METRNβ with IL10, IL6, and CCL7 was observed among the COVID-19 patients, while a negative correlation was observed with sCD40L." (PMID 36798115, 2023). "In conclusion, IL1-RA, IL-6, IFN-γ, G-CSF, CCL-7 and VEGF serum levels could prove helpful as biomarkers to assess disease severity and the need for intensive care in COVID-19 patients." (PMID 37917760, 2023).
COVID-19 (continued). "Serum CCL2, CCL3, CCL7, CXCL9, CXCL10, IL-1β and IL-1Ra levels increased in critical COVID-19 patients (n = 11) when compared to both severe COVID-19 patients (n = 25) and moderate COVID-19 patients (n = 14)." (PMID 36941580, 2023). "IL1-RA, IL-6, IFN-γ, G-CSF, CCL-7 and VEGF serum levels could prove helpful as biomarkers to assess disease severity and the need for intensive care in COVID-19 patients." (PMID 37917760, 2023). "Additionally, the level of multiple chemokines (IL-12p40, CCL2, CCL7, CXCL10, and M-CSF) was significantly increased in fatal COVID-19 cases." (PMID 35386707, 2022). "Moreover, the levels of IL-8, CCL2, CCL3, CCL4, CCL7, CCL12, and CX3CL1 were higher in both the serum and CSF samples of COVID-19 cases with neurological syndrome (NS)." (PMID 35464491, 2022). "In the BAL fluid of patients with COVID-19, significantly increased and extremely high levels of the cytokines IL-1β, IL-1RA, IL-17A, TNF-α, and G-CSF and the chemokines CCL7, CXCL1, CXCL8, CXCL11, and CXCL12α were found in comparison with BAL fluid of patients with influenza." (PMID 34793331, 2022). "In accordance with this, COVID-19 tissue studies show increased expression of CCL2 and CCL7, known to be chemotactic for macrophages, thus stressing the central role of the cytokine storm in COVID-19 pathogenesis and highlighting a potential therapeutic intervention in severe disease." (PMID 33950285, 2021). "Comparative proteomics identified statistically robust overexpression of several inflammatory cytokines, specifically IL6, IL18, CCL7, CXCL10, and CXCL11, which could be targeted to prevent untoward immune-inflammatory effects in COVID-19 patients." (PMID 35145507, 2021). "Moreover, increased circulating CCL7 may promote cytotoxic CD8+ T cell recruitment to the heart, with potentially deleterious effects on cardiac remodeling after COVID-19." (PMID 39444690, 2024). "First we compared the soluble proteome from aIFNpos COVID-19 patients to healthy individuals and observed a significant inflammatory response in aIFNpos patients with drastically elevated levels of proteins such as interleukin 6 (IL-6), IFN-γ, CXCL10, and CCL7." (PMID 38421006, 2024). "COVID-19-related cardiac injury in symptomatic patients with non-ischaemic myocarditis-like MRI abnormalities is associated with immune dysregulation, including decreased peripheral CD8 TEM cells and increased CCL7, persisting long after the initial infection." (PMID 39073768, 2024). "Severe COVID-19 in controls, but not SOT recipients, was associated with a marked increase in several canonical proinflammatory serum cytokines and chemokines (e.g., IL6, CCL7, and CXCL9)." (PMID 38196658, 2023). "In particular, mild COVID-19 is characterized by increase of IFN-α, IFN-γ, IL6, IL10, IL1RA [TE87, TE88, TE89], while severe disease is characterized by a downregulation of IFNα, and a parallel up-regulation of IFN-β, IFN-γ, IL6, TNF, IL10, CCL7 [TE89, TE90, TE94]." (PMID 34876157, 2021). "Thus, adipose IRF5 transcripts in obesity correlate positively with TNF-α, IL-1β, IL-6, CXCL8/IL-8, CXCL9/MIG, CXCL10/IP10, CCL2/MCP1, CCL5, and CCL7/MCP3, all of which can be elevated in COVID-19 “cytokine storm”; positive correlations with IL-2 and IL-12 have been reported by the same group." (PMID 33936053, 2021). "Mostly, markers of inflammation such as IL-6, IL-10, CXCL10 (also known as IP10), CXCL11, CCL2, CCL7, CCL8, PD-L1, and IL-18R1 were increased at the early stage of COVID-19 in ICU patients compared to non-ICU ones." (PMID 35269564, 2022).
Obesity (33 papers, 2012 to 2026). Accumulation of substantial excess body fat. "Obesity predisposes to higher secretion of chemokines (e.g., CCL7) by hypertrophic adipocyte cells from PPAT and secondarily facilitates extraprostatic extension, leading to locally advanced disease." (PMID 39941741, 2025). "The observed increase in migration associated with obesity is totally abrogated when the CCR3/CCL7 axis is inhibited, highlighting its key role in this altered condition." (PMID 26756352, 2016). "The observed increase in migration associated with obesity is totally abrogated when the CCR3/CCL7 axis is inhibited." (PMID 26756352, 2016). "Overexpression of CCL7 protects the organism in a mouse model of diet-induced obesity and hepatic steatosis." (PMID 39334887, 2024). "Our results showed CCR5 and CCL7 expression only in the obesity context (a 4-fold change and 15-fold change, respectively), while the HME1 cells cultured in the normal media without any additives showed no expression." (PMID 38247865, 2024). "In a mouse model of diet-induced obesity and hepatic steatosis, overexpression of CCL7 protects the organism from these diseases." (PMID 39334887, 2024). "In murine models of diet-induced obesity and hepatic steatosis, overexpression of CCL7 confers protection against these conditions." (PMID 39334887, 2024). "For example, obesity strongly promotes the process by which PPAT-secreting chemokine CCL7 stimulates the migration of CCR3-expressing tumor cells." (PMID 38164282, 2024). "As increased CCL7 levels are found in diabetes and obesity, preliminary studies on rodent models of hypersensitivity present in obesity are needed to assess the significance of CCL7 in these conditions." (PMID 39457105, 2024). "A prospective study of the general population with and without diabetes from the KORA cohort showed that serum levels of CCL7, CXCL10, and DNER partly mediated the association between obesity and PN." (PMID 35651981, 2022). "Upon inhibiting the CCR3/CCL7 axis, the observed obesity-potentiated tumor cell migration and invasion are nullified." (PMID 35406450, 2022). "Subsequently, in late obesity, we observed the overexpression of genes involved in anatomical structural morphogenesis, such as C–C motif chemokine ligand 7 (Ccl7), an important chemoattractant of leukocytes." (PMID 34805147, 2021). "A previous report showed that obesity-induced periprostatic adipocytes facilitated the extraprostatic extension of PCa cells by enhanced CCR3/CCL7 signaling." (PMID 29340091, 2017). "In lean conditions, the secretion of CCL7 was slightly higher in adipocytes than in the SVF, and a dramatic increase of CCL7 expression was observed in obesity only in mature adipocytes (around fivefold increase compared with lean conditions)." (PMID 26756352, 2016). "Here, the authors show that periprostatic adipose tissue promotes the migration and local invasion of prostate cancer cells by secreting the chemokine, CCL7, and that this process is enhanced in the context of obesity." (PMID 26756352, 2016). "For whole adipose tissue, the use of pharmacological inhibitors and CCR3/CCL7 blocking m/pAbs completely abrogated the increase of tumour cell migration observed in obesity." (PMID 26756352, 2016). "Additionally, CCR3/CCL7 axis blockade leads to inhibition of increased obesity-related cancer cell migration." (PMID 39941741, 2025). "Notably, CCL7 and its respective receptor CCR3, are upregulated in AT in human obesity and are associated with increased inflammation." (PMID 35406450, 2022). "We have previously demonstrated that CCL7 is the main CCR3 ligand regulated by obesity in PPAT." (PMID 33671469, 2021). "In addition, we observed that CCL7 secretion by BM-Ads was up-regulated by obesity and during ageing; an increased CCL7 secretion by PPAT of obese subjects having also been demonstrated in our previous study." (PMID 33671469, 2021).